GSK3B (glycogen synthase kinase 3 beta)
Diseases named in the same sentence as GSK3B in open-access papers (continued):
Sharing a sentence is not in itself a finding about the gene and the disease.
tumor (continued). "During the tumorigenesis process, the triggering of Wnt could prevent GSK-3β from activation and maintain β-catenin stabilization, which are highly correlated with tumor EMT." (PMID 29234238, 2017). "GSK3β also participates in neoplastic transformation and tumor development." (PMID 27494834, 2016). "To date, we have reported that GSK-3β is highly expressed in tumor nuclei of RCC." (PMID 27387559, 2016). "To further investigate the functions of both GSK3β and hnRNPK in TRAIL-induced tumor cell apoptosis, we have either knocked down or overexpressed GSK3β or hnRNPK respectively by transient transfection of H1299 cells with corresponding siRNA or Flag-tagged expression plasmids." (PMID 26972480, 2016). "In addition, NFκB activation is required for the induction of the CSN2/GSK3β pathway, which enhances tumor invasion and metastasis." (PMID 26942699, 2016). "In addition, all neoplasms harbored mutations that directly or indirectly affected either the regulation or activation of the PI3K pathway (PIK3CA, NF1, INPP5B and GSK3B)." (PMID 27057633, 2016). "Furthermore, we demonstrated that nuclear overexpression of GSK-3β and tumor proliferation in RCC are negatively regulated by miR-199, the only microRNA known to target GSK-3β." (PMID 27387559, 2016). "In addition, they showed that GSK-3β significantly reduced in vivo the size of tumor injected subcutaneously in a mouse xenograft model." (PMID 27387559, 2016). "Since GSK3β negatively regulates many oncoproteins and cell cycle regulators, it may function as a tumor suppressor." (PMID 27494834, 2016). "The nude mouse xenograft assay showed that miR-129 overexpression may suppress tumor growth through downregulating GSK-3β expression." (PMID 27050373, 2016). "This stems from the observation that GSK-3β promotes cell survival, proliferation and invasion by modulating distinct tumor suppressor pathways, cell immortality pathways and cell-motility machinery, thus rendering cancer cells resistant to chemotherapeutic agents and ionizing radiation." (PMID 27780915, 2016). "Indeed, GSK-3β functions in a wide range of tumor cellular processes including cell cycle, proliferation, angiogenesis, invasion and paclitaxel resistant." (PMID 28036353, 2016). "Furthermore, the repressive effects of SR48692 on NTS-induced EMT and tumor invasion were rescued by specific GSK-3β antagonist TPA in HCC cells." (PMID 27611941, 2016). "However, the roles of GSK3β in cancer are controversial, since it can act both as an oncogene product and as a tumor suppressor, depending on the context of the pathway circuits within a certain cell." (PMID 27525972, 2016). "However, the two key kinases in Wnt signaling, GSK-3β and CK1α, negatively regulate the Wnt/β-catenin signaling pathway, and therefore cannot serve as therapeutic targets for anti-tumor treatment." (PMID 26992223, 2016). "Interestingly, the authors also showed that the GSK3β inhibitor IX provoked strong steroid resistance in sensitive T-ALL tumor lines, further confirming the pivotal role of this molecule in the regulation of glucocorticoid resistance." (PMID 27997538, 2016). "In contrast to its therapeutic efficacy against tumor-initiating (cancer stem) cells, inhibition of GSK-3β positively regulates the pluripotency of embryonic stem cells and the repopulation of hematopoietic stem cells via activation of the Wnt and hedgehog pathways, respectively." (PMID 27780915, 2016). "GSK-3β overexpression decreased tumor growth by 65% compared to the Ad-GFP group." (PMID 26388612, 2015). "Nef-M1 treated tumor cells analyzed via western blot displayed increased expression of the epithelial signature E-cadherin and decreased expression of the mesenchymal signature vimentin, fibronectin, and p-GSK-3β." (PMID 26318034, 2015).
tumor (continued). "Taken together these data indicated that under proteasome stress cyclin E degradation is depending on GSK-3β activity, suggesting that chronic inhibition of GSK-3β could be responsible, at least in part, of the cell cycle alteration in these tumor cells." (PMID 25941117, 2015). "To further determine whether GSK-3β activation in U87 is sufficient in inhibiting tumor growth, we generated xenograft tumors by the injection of U87-GSK-3β or U87-GFP control cells subcutaneously into nude mice for 35 days." (PMID 26388612, 2015). "Taken together, these results strongly support that early autophagy activation in addition to GSK-3β chronic inhibition might be crucial for tumor cell recovery under proteasome stress." (PMID 25941117, 2015). "In summary, these results demonstrate that GSK-3β overexpression inhibits tumor growth." (PMID 26388612, 2015). "Similarly, the expression of GSK3β was observed in 83.3% normal (5/6), 83.3% PMLs (5/6) and 59.25% oral tumor (16/27) samples." (PMID 25645517, 2015). "Because growing evidence indicated that GSK-3β can be, directly or indirectly, involved in cell cycle progression we wondered whether cell cycle behavior of tumor cells under proteasome stress could be dependent, at least in part, on GSK-3β signaling." (PMID 25941117, 2015). "Previously, overexpression of c-Myc has been reported to induce EMT in mammary epithelial cells via ERK-dependent GSK-3β inactivation and subsequent snail activation and promote tumor cell invasion via activation of MEK-ERK signaling as well as MMPs expression." (PMID 26164082, 2015). "This experiment indicated that GSK3β can be regulated by p38MAPK in this tumor model." (PMID 25937997, 2014). "Moreover, the inhibition of GSK3β activity reduced cell survival and proliferation, induced apoptosis and suppressed tumor invasiveness." (PMID 24618715, 2014). "However, many studies have demonstrated that GSK3β can positively regulate the proliferation and apoptosis of tumor cells." (PMID 24618715, 2014). "GSK3β protein expression was increased in 14/29 (48%) of tumours (at p<0.05; Kruskal-Wallis test) when compared to the patient-matched normal tissue, decreased in 3/29 (10%) tumours (p<0.05) and unchanged in the remaining 12 tumours (i.e. p>0.05)." (PMID 25486534, 2014). "Moreover, in the experimental systems where GSK3B plays an oncogenic role its targeting has been proved useful, either alone on in combination with chemotherapy, to induce or increase tumor cells death." (PMID 24984063, 2014). "In order to investigate whether SFRP2 affects the growth of OSCC via the Wnt signaling pathway in nude mice, the expression levels of GSK-3β, β-catenin and cyclin D1 in tumor tissues were further analyzed by immunohistochemical analysis." (PMID 25189527, 2014). "Moreover, multivariate Cox regression analysis revealed that, in this group, tumor size, lymph node invasion and GSK3β expression were independent predictors of NSCLC prognosis." (PMID 24618715, 2014). "Furthermore, we examined the miR-135b or mRNA expression of GSK3β in tumor tissues from patients who received IR treatment." (PMID 25265336, 2014). "It is known that AKT can enhance tumor growth, by phosphorylating and inactivating GSK3β." (PMID 25311367, 2014). "While a number of studies support the idea of GSK3β being tumor suppressive, others studies showed that GSK3β may promote cancer development." (PMID 25238393, 2014). "The role of GSK3β in tumourigenesis and cancer progression remains controversial; it may function as a “tumour suppressor” for certain types of tumours but promotes growth and development for some others." (PMID 23874688, 2013). "Therefore, our immunoblot results showing preferentially increased phospho-GSK3β in 56Fe-irradiated tumor samples suggest an additional route of β-catenin activation and intestinal tumorigenesis after space radiation." (PMID 23555653, 2013).
tumor (continued). "These trials are rationally supported by the differential roles of GSK3β in cellular signaling events between normal and tumor cells and by the phosphorylation-dependent regulation of GSK3β activity that presumably protects normal cells from transformation by GSK3β inhibition." (PMID 23408967, 2013). "GSK3β also participates in neoplastic transformation and tumour development." (PMID 23874688, 2013). "Since GSK-3β is a pleiotropic kinase with a broad range of functions, it also appears to have multiple types of impact on carcinogenesis, with evidence supporting its tumorigenic influence and other evidence suggesting that it can inhibit tumor growth." (PMID 23840442, 2013). "Both groups of mice showed the similar levels of GSK3β expression in tumor xenografts." (PMID 23408967, 2013). "In contrast, GSK-3β is highly expressed in colorectal cancer and has been shown to participate in nuclear factor-κB (NF-κB) mediated cell survival in pancreatic cancer, thus behaving as a tumor promoter." (PMID 22675363, 2012). "The difference in gsk3β expression between the mono- and bi-transgenic tumor samples is striking: gsk3β is strongly up-regulated in tumors of mono-transgenic WAP-T mice (more than 30-fold) whereas in tumors of bi-transgenic mice gsk3β levels were similar to those of non-tumor samples." (PMID 22235331, 2012). "The distinct subcellular localizations noted for CDC2 and GSK3β in the different tumor types is interesting and may suggest distinct biological functions." (PMID 21660227, 2011). "GSK3β is, therefore, hypothesized to inhibit tumor development by interfering with oncogenic signaling (e.g., Wnt, hedgehog)." (PMID 24212624, 2011). "Little is known about the inherent tumorigenic property of ESCs, except that the oncogene Eras regulates the tumor-like growth of mESCs via activation of Akt1, which may result in inactivation of Gsk3β." (PMID 21731714, 2011). "Furthermore, TG2 induced the PI3K/Akt activation and GSK3β inactivation in A431 tumor cells and this increased Snail and MMP-9 expression resulting in higher cell motility." (PMID 21777419, 2011). "It is suggested with these data that the activity of Gsk3β orchestrates the tumor-like growth of ESCs, which may support a novel mechanism independent from the one regulating the pluripotency of ESCs." (PMID 21731714, 2011). "Because we reported that macrophages and IL-1β inactivate GSK3β in tumor cells, we next examined whether macrophages/IL-1β stabilize Snail through inhibition of GSK3β." (PMID 20661477, 2010). "Indeed, pharmacological inhibition of GSK3β by LiCL or by GSK3β specific inhibitor, AR-A014418, was sufficient to stabilize Snail in tumor cells." (PMID 20661477, 2010). "Since it has been also shown that GSK-3β regulates tumor cell survival through a NF-κB-dependent pathway we next tested whether GSK-3β inhibition by TDZD-8 could affect NF-κB activity in GL261 cells." (PMID 21079728, 2010). "Moreover, in HNSCC, p70S6K is reportedly very active, and targeting it with rapamycin has a potential anti-tumor effect in vivo, possibly due to the activation of GSK3β." (PMID 20537194, 2010). "Moreover, we found that expression of GSK-3β was higher in tumour compared with corresponding normal kidney tissue." (PMID 19920820, 2009). "If GSK-3β is inactivated, this could potentially lead to tumor promotion." (PMID 40157890, 2025). "Further studies to elucidate the precise molecular mechanisms underlying GSK-3β-mediated modulation of DC function may provide new strategies to optimize DC-based vaccines by temporally manipulating GSK-3β activity to enhance both acute anti-tumor immunity and long-term immune protection." (PMID 40649856, 2025).
tumor (continued). "In addition, encapsulated stem cells were able to trigger the expression of Wnt antagonists, such as Secreted Frizzled-related protein 4 (sFRP4), Dickkopf-1 (DKK1), and glycogen synthase kinase 3 beta (GSK-3β), downregulating the β-catenin pathway, which is involved in tumor promotion." (PMID 39936941, 2025). "However, the therapeutic implications of GSK3β inhibition remain complex, particularly due to concerns regarding off-target effects, systemic toxicity, and the paradoxical role of GSK3β as both a tumor suppressor and tumor promoter in different cellular contexts." (PMID 40573222, 2025). "Importantly, our work evokes a Wnt-regulated programme underlying tumour stemness in hybrid EMT cells via ERK activation, which might be due to RAS stabilisation by Wnt/GSK3β inhibition." (PMID 40764669, 2025). "In addition, we observed that anti-PDGF-BB antibodies and STI571 could significantly reduce the levels of p-GSK3β and p-P65 in tumor tissue in the subcutaneous tumor model, mainly occurring in tumor cells." (PMID 37307823, 2024). "Furthermore, we also identified GSK3B in tumor organoids treated with 4 and 8 Gy of radiation." (PMID 38429272, 2024). "In addition, inhibition of GSK3B by CP21R7 slowed tumor growth in xenograft models." (PMID 39166606, 2024). "Additionally, GSK-3β plays a role in shaping the tumor microenvironment by affecting the secretion of cytokines and growth factors that promote angiogenesis and immune evasion, facilitating tumor growth and metastasis (Massagué, 2004)." (PMID 39156976, 2024). "Thus, our study discovered that GSK3A and GSK3B are significantly activated in GAC primary tumor tissues from patients with lymph node metastasis, suggesting GSK3 may serve as a potential therapeutic target which warrants further validations." (PMID 36520032, 2023). "Indeed, GSK-3β’s tumor-promoting functions have been reported in 25 different cancer types." (PMID 37108703, 2023). "Hence, inactivated GSK3β helps increase PD-L1 stability and aids tumor immune escape." (PMID 37554324, 2023). "Finally, we propose a therapeutic alternative for TNBC patients, whose overexpression of NDRG1 is associated with poorer survival and TGFβ1 status, by the combination of TGFβ and GSK3β inhibitors to potentially preventing tumor progression, recurrence, and chemoresistance." (PMID 36594086, 2023). "Furthermore, palbociclib-insensitive tumours (two-cycles) showed reduced phosphorylation in AKT (p = 0.03) and RSK2 (p = 0.003), as well as the tumour suppressors p38 (p = 0.04) and GSK3a (p = 0.04) and GSK3b (p = 0.004) compared to palbociclib-sensitive tumours (one-cycle)." (PMID 37190140, 2023). "Besides, our study suggested that PCMT1 might regulate the migration, invasion and apoptosis of PCa cells by modulating the PI3K/AKT/GSK-3β signaling pathway and also can promote tumor growth in the in vivo." (PMID 37899170, 2023). "Additionally, histological examination of tumor sections showed that a significant amount of necrosis in the tumors of mice treated with combined DIM and 5-Fu treatment significantly decreased the protein expression of p-Akt and p-GSK-3β (Ser9) in xenograft tumor tissue." (PMID 36785670, 2023). "Therefore, Tumor progression may be facilitated by TROAP activating the PI3K/Akt/GSK3β signaling pathway." (PMID 36419876, 2022). "Furthermore, mapping drug target data to the top genes in our association prediction identifies inhibitors that could potentially enhance tumor response to anti-PD1, such as inhibitors of the encoded proteins of CDK4, GSK3B, and PTK2." (PMID 35013211, 2022). "However, in malignancies where GSK3β plays a tumor suppressor role but is inactivated by oncogenic pathways through S9-phosphorylation, GSK3β-targeted strategies could rely on the suppression of the inhibitory pathways." (PMID 36050315, 2022).
tumor (continued). "However, in the on state, Gsk-3β was inactivated through phosphorylation, and then β-catenin is accumulated in the cytoplasm so as to increase the nuclear localization of β-catenin, activating downstream target genes and modulating the behavior of tumor cells." (PMID 35433476, 2022). "Therefore, these PROTAC molecules might also be effective therapeutics in cancer settings where overactive GSK-3β plays a tumor-promoter role." (PMID 35681507, 2022). "Collectively, we found that exosomal miR-1290 from CAFs could promote tumor growth and metastasis via downregulating GSK3β/β-catenin signaling, suggesting that inhibiting CAFs-derived exosomal miR-1290 may provide a new modality for the treatment of growth and metastasis in PC." (PMID 35999213, 2022). "Moreover, Nrf2, HIF1α, and VEGF were significantly reduced in curcumin-treated As3+-exposed induced tumor samples, while inhibition of GSK3β could reverse the inhibitory effects of curcumin treatment." (PMID 34758851, 2021). "Finally, GSK3β inhibition leads to tumor growth retardation both in vitro and in vivo: whereas tumor masses in mice were significantly lower throughout the entire experiment, tumor volumes were significantly lower during most of the study, but not at the very end." (PMID 32767962, 2021). "In addition, inhibition of GSK-3β decreased CRC tumor cell growth in vitro and in vivo." (PMID 34955846, 2021). "Therefore, we shed light on the effect of RA on ADAM17 expression and found that RA considerably inhibited the expression of ADAM17 together with the downstream mediators of ADAM17, which constitutes ADAM17/EGFR/AKT/GSK3β axis and represents a crucial pathway for tumor progression." (PMID 34224305, 2021). "Thus, GSK3β is typically supposed as a ‘tumor-suppressor genes’." (PMID 33969873, 2021). "In conclusion, we identified a new candidate oncogenic lncRNA WFDC21P that promotes tumor progression through WFDC21P/Ran/Akt/GSK3β/β-catenin axis and that is positively regulated by transcription factor FOXP3 in GC, which may provide a novel biomarker and therapeutic target for GC." (PMID 34601496, 2021). "In response to transforming growth factor beta (TGF-β), ERK kinase inactivates GSK3β, resulting in Snail protein accumulation and promotion of epithelial-mesenchymal transition (EMT), which is characterized by the loss of cell polarity and serves as a pre-condition for tumor invasion and metastasis." (PMID 32767962, 2021). "Accumulating evidence has found that the Akt/GSK3β pathway can accelerate cell cycle progression in various types of tumours, and a previous study reported that Akt signalling could promote survival or inhibit apoptosis through substrates mediated in proportion by NF-κB." (PMID 34380537, 2021). "Thus, altering the levels of GSK-3β can have dramatic effects on sensitivity to drugs and signal transduction inhibitors which may be influenced by the background of the tumor." (PMID 33917370, 2021). "Besides, as the downstream molecule of PI3K/Akt, GSK3β participates in multiple signal pathways and its inactivation in hypoxia may contribute to angiogenesis and tumor growth by facilitating HIF-1α." (PMID 34329303, 2021). "Some studies have reported that GSK-3β may function as a tumour promoter." (PMID 32211045, 2020). "Thus, certain PPARγ agonists may function by suppressing GSK-3β, which in this scenario, was eliciting tumor promoter effects." (PMID 32365809, 2020). "It was demonstrated that VE-cadherin expression and downstream activation of the Akt/GSK3β/β-catenin signaling caused an increase in the expression of the chemokine (C-C motif) ligand 2 (CCL2) and CXCL10, which facilitate CD8+ T cell transmigration into tumor parenchyma." (PMID 33276489, 2020). "Finally, we confirmed that GPNCA silencing could inhibit HepG2 and HCT116 tumor cell growth via regulating its nearby gene GSK3B." (PMID 32029792, 2020).